CDK12 (cyclin dependent kinase 12)
Diseases named in the same sentence as CDK12 in open-access papers (continued):
Sharing a sentence is not in itself a finding about the gene and the disease.
metastatic disease (7 papers, 2019 to 2025). "Patients with CDK12 mutations have had clinical features associated with poor prognosis, including a higher novo metastatic disease prevalence, higher PSA at diagnosis, and a higher Gleason score eight predominance." (PMID 39935910, 2025). "In contrast to pPCa, metastatic tumors harboring CDK12 alterations expressing low levels of MHC-I/II showed allele-specific copy number gains in the MHC-I/II complex and key regulators of MHC expression." (PMID 38704603, 2024). "Of patients with metastatic disease (n = 2997), 1.1% (n = 32) were identified to a pathogenic CDK12 alteration compared to 0.36% (n = 7) in patients with localized disease (n = 1937)." (PMID 34898046, 2022). "In each patient, all metastatic tumors shared the same CDK12 alteration, and all tumors exhibited a TDP with the majority of TDs shared across tumors within an individual." (PMID 39071291, 2025). "Patients with the CDK12 mutation have demonstrated a shorter time from ADT introduction to castration resistance and OS from metastatic disease diagnosis." (PMID 39935910, 2025). "We searched the cBioPortal and GENIE Project (public release v4.1) databases for cancer types with > 200 sequenced cases, that included patients with metastatic disease, and in which the occurrence of at least monoallelic CDK12 alterations was > 1%." (PMID 31360735, 2019).
bladder cancer (5 papers, 2019 to 2025). "The prevalence of at least monoallelic CDK12 mutations was highest in bladder cancer (3.7%); followed by prostate (3.4%), esophago-gastric (2.1%) and uterine cancers (2.1%)." (PMID 31360735, 2019). "CDK12 mutations are frequently found in human tumors, including bladder cancer." (PMID 41312368, 2025).
leukemia (5 papers, 2020 to 2026). A malignant (clonal) hematologic disorder, involving hematopoietic stem cells and characterized by the presence of primitive or atypical myeloid or lymphoid cells in the bone marrow and the blood. "Inhibiting CDK9 or CDK12/13 induced the rapid downregulation of the short-lived, anti-apoptotic Bcl-2 proteins Mcl1 and A1/Bfl1 in Jurkat leukemia cells and SUDHL1 lymphoma cells, whereas the expression of Bcl-2 and Bcl-xL remained unaffected." (PMID 42204137, 2026). "Our data show that CDK12 is crucial for the growth of NUP98::KDM5A-driven leukemia in vitro and in vivo and that small-molecule-mediated perturbation of CDK12 leads to a profound downregulation of genes involved in DNA repair, as reported in previous studies." (PMID 40389480, 2025). "Among AML patients, NUP98 fusion-driven leukemia patients (n = 11) showed even higher CDK12 expression, with highest levels detected in NUP98::KDM5A AML (n = 4)." (PMID 40389480, 2025). "However, its role in preventing excessive accumulation of DNA damage via the efficient induction of repair mechanisms likely represents one aspect amongst the broader role of CDK12 in mediating leukemia cell survival." (PMID 40389480, 2025).
osteosarcoma (5 papers, 2019 to 2026). A usually aggressive malignant bone-forming mesenchymal neoplasm, predominantly affecting adolescents and young adults. "Knockout of CDK12 in an in vivo osteosarcoma model of lung metastasis significantly decreased the ability of OS to metastasize the lung." (PMID 33686962, 2021). "CDK12 has been found as a metastatic vulnerability in osteosarcoma." (PMID 41491919, 2026). "In a murine osteosarcoma metastasis model, CDK12 knockout markedly reduced lung metastases." (PMID 41491919, 2026). "In osteosarcoma cells, CDK12 could also play a role in transcriptional regulation of the MAP3K14 and NFKB2 mRNA expression, participating in activation of noncanonical NF-κB pathway." (PMID 31523177, 2019). "CDK12 has been reported to facilitate genome stability through the regulation of DDR genes; accordingly, the CDK12 inhibitors THZ531 and E9 were found to disrupt osteosarcoma metastasis." (PMID 37197432, 2023).
pancreatic cancer (5 papers, 2020 to 2025). "Pancreatic cancer showed an exceptionally high biallelic loss in HRR genes, with BRCA1, CDK12, FANCC, PPP2R2 A, RAD51 C, RAD51D, RAD52, WRN, and XRCC3 all presenting 100% biallelic loss." (PMID 40420266, 2025).
prostate tumors (5 papers, 2019 to 2024). "The authors found that this mechanism is preserved in ovarian and prostate tumors with CDK12 loss-of-function mutations or deletions." (PMID 30988284, 2019). "Furthermore, it is unclear whether CDK12 loss renders prostate tumors susceptible to paralog-based synthetic lethality." (PMID 39368479, 2024). "Murine and human prostate tumors with inactive CDK12 exhibit paralog-based synthetic lethality upon pharmacologic targeting of CDK13—a strategy with potential clinical application." (PMID 39368479, 2024). "Compared with Pten-null animals with intact Cdk12, these double knockout mice demonstrated improved survival and markedly reduced prostate tumor size, as well as impaired mTOR signaling." (PMID 39368479, 2024). "Analyses of ovarian and prostate tumours with biallelic inactivation of CDK12 revealed a unique genome instability phenotype characterized by copy-number gains." (PMID 34316683, 2020). "However, CDK12-inactivated ovarian and prostate tumours present a unique genome instability phenotype, pointing to a unique deregulation of genome stability (likely by aberrant DNA replication-associated HR-dependent repair) leading to tumorigenesis." (PMID 34316683, 2020).
medulloblastoma (4 papers, 2021 to 2025). A malignant, invasive embryonal neoplasm arising from the cerebellum. "THZ1 inhibits CDK7, CDK12, and CDK13 and was described as radiosensitizer in a study on medulloblastomas." (PMID 34063457, 2021). "In this regard, it was demonstrated that the TA-CDK inhibitors THZ1, which simultaneously inhibits CDK7, CDK12 and CDK13, and THZ531, which selectively targets CDK12/13, strongly impaired viability of medulloblastoma (MB) cells, with a significant selectivity toward MYC-amplified cell lines." (PMID 39533070, 2025).
neuroblastoma (4 papers, 2018 to 2023). Neuroblastoma (NB) is the most common solid, extracranial childhood tumor. "We focused on the ALK, IGF1, WNT, EZH2/PRC2, BET, CDK7, and CDK12/13 signaling pathways since they have been shown to be important during the normal development of sympathoadrenal cells and/or involved in neuroblastoma tumorigenesis." (PMID 35681734, 2022). "The CDK7 covalent inhibitor THZ1, which also inhibits the closely related kinases CDK12 and CDK13 (CDK12/13), has been also shown to directly suppress super-enhancer-associated oncogenic transcription in T-cell acute lymphoblastic leukemia, neuroblastoma and small cell lung cancer." (PMID 30422115, 2018). "While THZ1 appears to preferentially affect genes controlled by super-enhancers in neuroblastoma, MYCN-dependent genes in particular, there is evidence to indicate that the off-target inhibition of CDK12 and CDK13 rather than of CDK7 is responsible for the transcriptional effects of THZ1." (PMID 35681734, 2022).
anemia (3 papers, 2022 to 2025). A reduction in the number of red blood cells, the amount of hemoglobin, and/or the volume of packed red blood cells. "CDK12 is involved in the DNA-damage repair (DDR) pathway by regulating the expression of several DDR machinery components, including BRCA1, ATM, ATR, and Fanconi anemia (FANC) genes." (PMID 40148269, 2025).
endometrial cancer (3 papers, 2020 to 2025). Primary or metastatic malignant neoplasm involving the endometrium (mucous membrane that lines the endometrial cavity). "Lower HRD rates in endometrial cancers (10–15%) and assay insensitivity to non-BRCA genes (e.g., ATM, CDK12) demand cancer-specific validation." (PMID 40864792, 2025).
gastric tumor (3 papers, 2019 to 2022). "To measure CDK12 expression level in human gastric tumors, we performed immunohistochemistry (IHC) staining in human gastric tumor and adjacent tissues." (PMID 32483448, 2020).
glioblastoma (3 papers, 2022 to 2026). The most malignant astrocytic tumor (WHO grade IV). "To identify new therapeutic vulnerabilities, we investigated the role of CDK12, a transcription-associated cyclin-dependent kinase, in glioblastoma." (PMID 40996961, 2025). "This CDK12/GSK3β/PPARD axis was required for glioblastoma cell proliferation and metabolic homeostasis." (PMID 40996961, 2025). "Here we find that glioblastoma stem cells (GSCs) are selectively sensitive to CDK12/CDK13 inhibition, whereas CDK7 and CDK9 inhibition cause non-specific cytotoxicity." (PMID 41882177, 2026). "Targeting the protein CDK12 is a promising therapeutic approach for glioblastoma." (PMID 40996961, 2025).
hepatocellular carcinoma (3 papers, 2024 to 2026). A malignant tumor that arises from hepatocytes. "In addition, the research team discovered that CDK12 is widely expressed in hepatocellular carcinoma (HCC) cell lines, confirming its critical role in HCC cell proliferation." (PMID 38503865, 2024). "Using a model of chemically induced hepatocellular carcinoma in mouse liver, we comparatively analyzed the dynamics of transcript levels for several genes (BRCA1, BRCA2, CHEK1, CHEK2, ATM, CDK12) in paired samples of normal and tumor tissue over a 24-h PMI using RT-qPCR." (PMID 42073491, 2026). "Transcriptomic analyses of TCGA datasets reveal significantly elevated CDK12 expression in hepatocellular carcinoma (HCC) compared with non-tumor liver tissue, correlating with poorer overall survival." (PMID 41491919, 2026).
uterine cancer (3 papers, 2019 to 2022). Primary or metastatic malignant neoplasm involving the uterine corpus and/or the cervix. "ATM, BRCA, CHECK2, and CDK12 mutations were frequent in cholangiocarcinoma (N = 34) with similar results in uterine carcinoma (N = 57), though the significance of these results is limited by small sample sizes." (PMID 33214570, 2020). "The gene CDK12 is a candidate within a region affected in 14.9% of the uterine cancer cohort." (PMID 36163358, 2022).
acute myeloid leukemia (2 papers, 2023 to 2025). Acute myeloid leukemia (AML) is a group of neoplasms arising from precursor cells committed to the myeloid cell-line differentiation. "CDK12 is an oncogene which is up-regulated and has highest expression level in Acute Myeloid Leukemia (AML), while its partner boundary non-oncogene PSMD3 shows down-regulation in AML patients." (PMID 38105946, 2023). "CDK12 is an oncogene, which is up-regulated and has the highest expression level in Acute Myeloid Leukemia (AML), while its boundary partner non-oncogene PSMD3 shows down-regulation in AML patients." (PMID 40051047, 2025).
asthma (2 papers, 2018 to 2020). "One of the major findings was the identification of the ORMDL3 (ORM1-like protein 3) and the GSDMB (Gasdermin-B) genes within 17q21 locus and CDK12 (Cyclin-dependent kinase 12) as candidate genes for childhood-onset severe asthma." (PMID 29992143, 2018).
brain tumor (2 papers, 2023 to 2025). "Lastly, we provide an overview of CDK12/13 inhibitors and of their efficacy in brain tumours and other neoplastic diseases." (PMID 39533070, 2025). "Our study demonstrates that CDK12/13 activity represents an exploitable vulnerability in MYC-high Group 3 MB and may pave the ground for new therapeutic approaches for this high-risk brain tumor." (PMID 37599362, 2023). "Moreover, mounting evidence also suggest the involvement of CDK12/13 in brain tumours." (PMID 39533070, 2025). "Thus, our study points to CDK12/13 activity as an exploitable vulnerability for this high-risk brain tumor, for which no targeted therapies are currently available." (PMID 37599362, 2023).
cervical cancer (2 papers, 2021 to 2022). A primary or metastatic malignant neoplasm involving the cervix. "The purpose of this study is to explore the exact functions and underlying mechanisms of CDK12 for tumorigenesis and proliferation in cervical cancer." (PMID 33628849, 2021). "Further investigations demonstrated that CDK12 promoted macrophage infiltration and regulated the immune microenvironment in cervical cancer cells." (PMID 33628849, 2021). "To investigate the potential mechanism of CDK12 in cervical cancer, we performed high throughput transcriptome sequencing (RNA-seq) analysis to compare the transcriptome for two groups: shNC and shCDK12 groups, respectively." (PMID 33628849, 2021). "CDK12 promoted cervical cancer progression by enhancing macrophage infiltration." (PMID 36463205, 2022). "The gene mutation and amplification of CDK12 were found in different types of malignancies by analyzing The Cancer Genome Atlas (TCGA) databases, such as amplification of CDK12 in cervical cancer (CC), which suggested that CDK12 had some properties of an oncogene." (PMID 33628849, 2021). "In this report, we investigated the role of CDK12 in cervical cancer." (PMID 33628849, 2021). "Knockdown of CDK12 inhibits the cell cycle process and proliferation in cervical cancer cells." (PMID 33628849, 2021). "Similarly, in the present study, we found that the knockdown of CDK12 inhibited progression from G1 to S phase and DNA replication in cervical cancer cells." (PMID 33628849, 2021). "Therefore, we employed flow cytometry to examine the effect of CDK12 on cervical cancer cell-cycle progression." (PMID 33628849, 2021). "Therefore, we believe that CDK12 may be a poor prognostic marker for cervical cancer." (PMID 33628849, 2021). "In the present study, we also found that knockdown of CDK12 with shRNA or THZ531 treatment inhibited cell proliferation, suppressed colony formation, and promoted their apoptosis in cervical cancer cells." (PMID 33628849, 2021). "In the present study, the expression of CDK12 was remarkably elevated in cervical cancer compared with normal cervical and tended to have a poor prognosis." (PMID 33628849, 2021).
chordoma (2 papers, 2022). Chordomas are rare malignant tumors arising from embryonic remnants of the notochord in axial skeleton. "CDK inhibitors such as THZ1, NVP-2 and THZ531 that inhibit CDK7, CDK9, CDK12 and CDK13, respectively, have been shown to downregulate SE-related oncogene expression and promote DNA damage response gene loss in chordoma and acute T-lymphoblastic leukaemia cells, respectively." (PMID 35514959, 2022).
diffuse large B-cell lymphoma (2 papers, 2022 to 2024). "On the other hand, CCNK is complexed with kinase CDK12 and CDK13, which are strongly associated with BRCA, AML and diffuse large B-cell lymphoma (DLBCL)." (PMID 38459430, 2024). "In diffuse large B-cell lymphoma, CDK12 activated MYC to inhibit miR-28-5p/EZH2 and amplify BCR signaling to promote its progression." (PMID 36463205, 2022).
glioma (2 papers, 2024 to 2025). A benign or malignant brain and spinal cord tumor that arises from glial cells (astrocytes, oligodendrocytes, ependymal cells). "The specific mechanism involves METTL3 stabilizing the mRNAs of BUD13 and CDK12, leading to their overexpression, which in turn promotes the phosphorylation of MBNL1 and facilitates the VM process in gliomas." (PMID 40469294, 2025). "It stabilizes the mRNAs of BUD13 and CDK12, thereby promoting MBNL1 phosphorylation and subsequently facilitating the formation of glioma vasculogenic mimicry (VM)." (PMID 40469294, 2025).
invasive breast carcinoma (2 papers, 2021 to 2024). A carcinoma that infiltrates the breast parenchyma. "There were no CDK12 gene amplifications reported in 44,293 invasive breast carcinomas in the FMI Insights CGP database." (PMID 38335502, 2024). "No CDK12 gene amplifications were reported in 44,293 invasive breast carcinomas." (PMID 38335502, 2024).
invasive lobular breast carcinoma (2 papers, 2021 to 2024). An infiltrating lobular adenocarcinoma of the breast. "According to our knowledge and most current literature data, this is the first study to provide comprehensive molecular data on HER2‐positive invasive lobular carcinoma and demonstrating that CDK12/HER2 gene coamplification is a common underlying mechanism in this subgroup." (PMID 38335502, 2024).
lobular breast carcinoma (2 papers, 2021 to 2024). "The underlying CDK12/HER2 gene coamplification, which is substantially detectable in our HER2‐positive lobular breast carcinoma cohort, is a characteristic molecular phenomenon in this subgroup, possibly contributing to poor prognostic behavior." (PMID 38335502, 2024).
lung adenocarcinoma (2 papers, 2023 to 2024). A carcinoma that arises from the lung and is characterized by the presence of malignant glandular epithelial cells. "Taken together, the results of this study suggest that inhibition of CDK12/13 in combination with osimertinib has the potential to overcome osimertinib resistance in EGFR mutant lung adenocarcinoma patients." (PMID 37190191, 2023). "These resistant human lung adenocarcinoma cell lines were tested for growth inhibition in vitro by two novel CDK12/13 inhibitors." (PMID 37190191, 2023). "In this study, we leveraged the availability of CDK12/13 inhibitor AU-15606 and AU-16770 to test if these compounds could overcome osimertinib resistance in lung adenocarcinoma cells." (PMID 37190191, 2023). "Here, we investigated the efficacy of two novel CDK12/13 inhibitors, AU-15506 and AU-16770, in osimertinib-resistant EGFR mutant lung adenocarcinoma cells in culture and xenograft models in vivo." (PMID 37190191, 2023).
metastatic cancer (2 papers, 2021 to 2022). A carcinoma which has spread from the original site of growth to another anatomic site. "NOTCH2, NOTCH2NL, KIF5B, and ERBB4 are highly expressed in primary cancer, while ERBB2, CLDN11 and CDK12 are overexpressed in metastatic cancer." (PMID 33441952, 2021). "Population-wide comparison between TT and LN single cells revealed that NOTCH2, NOTCH2NL, KIF5B, and ERBB4 are highly expressed in primary cancer, while CDK12, ERBB2, and CLDN11 are overexpressed in metastatic cancer." (PMID 33441952, 2021).
metastatic melanoma (2 papers, 2025 to 2026). A melanoma that has spread from its primary site to another anatomic site. "We first analyzed RNA sequencing data from tumor samples collected prior to ICB treatment in 2 metastatic melanoma cohorts and found that low expression of CDK12/13 (bottom 20th percentile) was significantly associated with improved overall survival." (PMID 40955658, 2025).
mismatch repair deficiency (2 papers, 2020 to 2023). "A study to assess the activity and efficacy ofpembrolizumab in participants with progressive metastatic castration-resistantprostate cancer, characterized by a mismatch repair deficiency orbiallelic CDK12 inactivation." (PMID 33135887, 2020).
Ovarian tumors (2 papers, 2020 to 2025). "While this model revealed the impact of Cdk12 loss on ovarian tumor progression, intraperitoneal administration of tumor cells from m-sgPRN;Cdk12KO mice enabled us to further demonstrate the importance of Cdk12 inactivation to tumorigenesis." (PMID 40504161, 2025). "The kinase has a pleiotropic effect on the maintenance of genome stability, and its inactivation in prostate and ovarian tumours results in focal tandem duplications, a CDK12-unique genome instability phenotype." (PMID 34316683, 2020).
skin cancer (2 papers, 2020 to 2026). "Given the high tumor mutational burden associated with skin cancer, further studies investigating if CDK12/13 mutations contribute to this genomic instability are warranted." (PMID 41491919, 2026).
carcinoid (1 paper, 2021). "Primary carcinoid S1 showed one private somatic mutation in the CDK12 gene (p.Arg44Leu), whereas the adenocarcinoma component of metastatic site showed a private mutation in the NOTCH1 gene (p.Pro498Arg)." (PMID 34926584, 2021).